DNA2 (DNA replication helicase/nuclease 2)
Description:
Key enzyme involved in DNA replication and DNA repair in nucleus and mitochondrion. Involved in Okazaki fragments processing by cleaving long flaps that escape FEN1: flaps that are longer than 27 nucleotides are coated by replication protein A complex (RPA), leading to recruit DNA2 which cleaves the flap until it is too short to bind RPA and becomes a substrate for FEN1. Also involved in 5'-end resection of DNA during double-strand break (DSB) repair: recruited by BLM and mediates the cleavage of 5'-ssDNA, while the 3'-ssDNA cleavage is prevented by the presence of RPA. Also involved in DNA replication checkpoint independently of Okazaki fragments processing. Possesses different enzymatic activities, such as single-stranded DNA (ssDNA)- dependent ATPase, 5'-3' helicase and endonuclease activities. While the ATPase and endonuclease activities are well-defined and play a key role in Okazaki fragments processing and DSB repair, the 5'-3' DNA helicase activity is subject to debate. According to various reports, the helicase activity is absent to weak and its function remains largely unclear. Helicase activity may promote the motion of DNA2 on the flap, helping the nuclease function.
Synonyms: hDNA2; DNA2L; KIAA0083; RTS4
Tractability: PROTAC: ubiquitination databases record sites on it.
Target class: Enzyme; Hydrolase
Gene: Protein-coding gene on chromosome 10 (68,414,061 to 68,472,121, reverse strand). Ensembl gene ENSG00000138346.
Subcellular location: Nucleus; Mitochondrion
Subcellular location (Human Protein Atlas): Mitochondria
Pathways (Reactome):
DNA Repair: HDR through Homologous Recombination (HRR); HDR through Single Strand Annealing (SSA); Homologous DNA Pairing and Strand Exchange; Presynaptic phase of homologous DNA pairing and strand exchange; Processing of DNA double-strand break ends; Resolution of D-loop Structures through Holliday Junction Intermediates; Resolution of D-loop Structures through Synthesis-Dependent Strand Annealing (SDSA)
Disease: Defective HDR through Homologous Recombination Repair (HRR) due to PALB2 loss of BRCA1 binding function; Defective HDR through Homologous Recombination Repair (HRR) due to PALB2 loss of BRCA2/RAD51/RAD51C binding function; Defective homologous recombination repair (HRR) due to BRCA1 loss of function; Impaired BRCA2 binding to PALB2; Impaired BRCA2 binding to RAD51
Cell Cycle: G2/M DNA damage checkpoint; Removal of the Flap Intermediate from the C-strand
DNA Replication: Removal of the Flap Intermediate
Gene Ontology:
Molecular function: 5'-3' DNA helicase activity; 5'-flap endonuclease activity; ATP hydrolysis activity; deoxyribonuclease (pyrimidine dimer) activity; DNA binding; DNA helicase activity; nuclease activity; protein binding; single-stranded DNA helicase activity; helicase activity
Biological process: base-excision repair; DNA double-strand break processing; DNA replication; DNA replication checkpoint signaling; DNA replication, Okazaki fragment processing; DNA replication, removal of RNA primer; mitochondrial DNA repair; mitochondrial DNA replication; positive regulation of DNA replication; DNA geometric change; mitotic telomere maintenance via semi-conservative replication; replication fork reversal; t-circle formation; telomere maintenance; telomere maintenance via semi-conservative replication
Cellular component: mitochondrial nucleoid; mitochondrion; nucleus; chromosome, telomeric region; cytoplasm; nucleoplasm
Genetic constraint (gnomAD): Loss-of-function variants: 84 observed, 90.35 expected, observed/expected ratio (o/e) 0.93, 90% interval 0.78 to 1.12. The upper end of that interval is the gene's LOEUF score, 1.12, which puts it in group 4 of 6, group 1 being the genes least tolerant of losing a copy. Missense variants: 1,003 observed, 1,114.9 expected, observed/expected ratio (o/e) 0.9, 90% interval 0.85 to 0.95. Synonymous variants: 330 observed, 378.83 expected, observed/expected ratio (o/e) 0.87, 90% interval 0.8 to 0.95.
Gene-disease validity (ClinGen):
ClinGen rates the evidence that DNA2 causes each of these diseases.
mitochondrial disease (autosomal dominant): Moderate.
Homologues: Orthologues: macaque DNA2 (95% identical), chimpanzee DNA2 (94% identical), dog DNA2 (88% identical), rabbit DNA2 (88% identical), pig DNA2 (85% identical), guinea pig DNA2 (82% identical), mouse Dna2 (80% identical), rat Dna2 (80% identical), tropical clawed frog dna2 (59% identical), Caenorhabditis elegans Y106G6D.5 (14% identical), Drosophila melanogaster CG6701 (13% identical), Drosophila melanogaster Mov10 (12% identical), and 2 more. Paralogues in human: HELZ2 (21% identical), SETX (18% identical), MOV10L1 (16% identical), IGHMBP2 (15% identical), ZNFX1 (15% identical), AQR (15% identical), HELZ (14% identical), UPF1 (14% identical), MOV10 (13% identical), CT55 (2% identical).
Diseases named in the same sentence as DNA2 in open-access papers:
DNA2 is named in the same sentence as 58 diseases in open-access papers, as found by Europe PMC text mining. Sharing a sentence is not in itself a finding about the gene and the disease. The quoted sentences say what the papers report.
Seckel syndrome (11 papers, 2016 to 2025). A rare autosomal recessive inherited syndrome caused by mutations in the ATR gene, RBBP8 gene, CENPJ gene, CEP152 gene, CEP63 gene, NIN gene, DNA2 gene, or TRAIP gene. "The DNA2 T665A mutation can be expected to have a severe and specific effect on the ATPase/helicase activity, providing a tentative link between Seckel syndrome and RF recovery, a function that clearly requires DNA2 helicase activity in vivo." (PMID 33924313, 2021). "In human, DNA2 mutations result in the primordial dwarfism disorder Seckel syndrome and have been linked to mitochondrial myopathy." (PMID 33924313, 2021). "Our results reveal the essential nature of Dna2-dependent RF recovery, suggesting that DNA2 falls into the same category of Seckel syndrome genes and that RF recovery defects in DNA2-deficient human cells are directly disease-relevant." (PMID 32544229, 2020). "These new insights disambiguate the effects of DNA2 dysfunction on cell survival, and provide a framework to rationalize the association of DNA2 with cancer and the primordial dwarfism disorder Seckel syndrome based on its role in RF recovery." (PMID 32909097, 2020). "More recently (January 2011-February 2014), mutations in for example RBBP8, CEP152 and DNA2 were found to cause Seckel syndrome: SCKL2, October 2011; SCKL5, January 2011; SCKL8, February 2014, respectively." (PMID 26919047, 2016). "Stochastic entry into senescence stifles the proliferative potential of cells following the expression of a Seckel syndrome patient-derived DNA2 hypomorph or partial degradation of DNA2, providing a conceptual framework to explain global growth failure in DNA2-linked primordial dwarfism disorders." (PMID 40903580, 2025). "The involvement of Dna2 helicase activity in completing replication may have implications for DNA2-associated pathologies, including cancer and Seckel syndrome." (PMID 27779184, 2016). "Some Seckel syndrome genes suggest striking parallels to DNA2′s function in RF recovery and replication completion." (PMID 33924313, 2021). "The critical nature of Dna2’s role in controlling the fate of stalled RFs provides a framework to rationalize the involvement of DNA2 in Seckel syndrome and cancer." (PMID 32544229, 2020). "Mutations in DNA2 that result in strongly reduced protein levels and/or dysfunction of DNA2’s helicase activity have been identified in patients with Seckel syndrome and microcephalic primordial dwarfism." (PMID 32544229, 2020). "Seckel syndrome is genetically heterogeneous, and mutations in DDR genes (ATRIP and ATR), DNA repair factors (NSMCE2, DNA2, TRAIP and CtIP) and components of the centrosome (NIN, CEP63, CEP152 and CENPJ) have been reported." (PMID 32994318, 2020). "Other forms of Seckel syndrome are caused by mutations in genes associated with cell growth (TRAIP), genomic integrity and repair (ATR, NSMCE2, DNA2, and RBBP8), centrosome function (NIN, CEP63)." (PMID 29504900, 2018). "Like mitochondrial myopathy, Seckel syndrome is genetically heterogeneous and disease mutations affect groups of genes with roles in DNA replication/repair (ATR, DNA2, CTIP, NSMCE2, and TRAIP) and segregation of the replicated genome into daughter cells (CEP63, CEP152, CENPJ, NIN, and NSMCE2)." (PMID 33924313, 2021).
breast cancer (8 papers, 2014 to 2024). A primary or metastatic malignant neoplasm involving the breast. "This is supported by the fact that overexpression of DNA2 blocks the MRE11-mediated fork degradation in Brca2-deficient mouse mammary tumor cells." (PMID 38271119, 2024). "Here, we found elevated DNA2 expression was closely associated with poor prognosis in breast cancer." (PMID 33574966, 2021). "In our study, we found increased expression of DNA2 in breast cancer was closely associated with ER (-), PR (-), HER (+), and predicted poor prognosis." (PMID 33574966, 2021). "We found that elevated expression of DNA2 was obviously linked to poor prognosis in breast cancer." (PMID 33574966, 2021). "However, the underlying mechanism of DNA2 in breast cancer and subtypes still needs to be defined and be helpful to develop new drugs for cancer therapy." (PMID 33574966, 2021). "We further exploit the synthetic lethality potential of DNA2 in ovarian and breast cancers by taking advantage of the role of DNA2 in HR repair." (PMID 37756561, 2023). "All the data strongly suggests that high expression of DNA2 is correlated with worse outcome in breast cancer." (PMID 33574966, 2021). "The results showed that high DNA2 expression was related to breast cancer cell cycle, DNA replication, homologous recombination, mismatch repair, nucleotide excision repair, and base excision repair pathways." (PMID 33574966, 2021). "To further detect the role of DNA2 in breast cancer cells, we took GESA, GO, and KEGG analyses and found that DNA2 was enriched in cell cycle and DNA replication pathways." (PMID 33574966, 2021). "Our research reveals that DNA2 is a biomarker for diagnosis and prognosis in breast cancer from multiple perspectives and gives a new clue for further preclinical and clinical investigation." (PMID 33574966, 2021). "DNA2 overexpression was reported in a breast cancer cohort with significant higher expression in basal-like breast cancer more than other subtypes, and it positively correlated to metastasis." (PMID 33662042, 2021). "We also predicted the potential mechanism of DNA2 action in breast cancer using functional and pathway enrichment analysis." (PMID 33574966, 2021). "There is an article that refers to the high expression of DNA2 in breast cancer predicts worse overall survival based on a study on 295 breast cancer cases." (PMID 33574966, 2021). "The survival curves obtained from the KM plotter suggested that DNA2 high expression was correlated to worse overall survival (OS) for all breast cancer patients, hazard ratio (HR) = 1.31(1.03 − 1.65), p = 0.024." (PMID 33574966, 2021). "Here, we investigated the detailed clinical attribute of DNA2 in breast cancer and the role of DNA2 in breast cancer cells' growth." (PMID 33574966, 2021). "Depletion of DNA2 in the breast cancer cell line MCF7 suppressed the anti-proliferative effect of C5, suggesting that DNA2 is the target of the compound in vivo." (PMID 29998112, 2018). "Initially, we compared the impact of our DNA2 inhibitor in pancreatic or breast cancer cells versus control cells." (PMID 28414320, 2017). "Kaplan-Meier (KM) curves, which are defined as the probability of surviving for a given length of time, show that in patients with breast cancer, DNA2 expression is inversely correlated with the duration of overall patient survival." (PMID 25238049, 2014). "Moreover, we also screened DNA2-related signaling pathways in breast cancer to understand the potential mechanism involved in the regulation of breast cancer development by DNA2." (PMID 33574966, 2021). "Our results showed that high expression of DNA2 in breast cancer predicted poor prognosis." (PMID 33574966, 2021). "It has recently been found that DNA2 is highly expressed in breast cancer tissues." (PMID 33574966, 2021).
breast cancer (continued). "As mentioned in studies, DNA2 high expression not only occurred in breast and ovarian cancers, but also in liver cancer, testis cancer, thyroid cancer, endometrial cancer, carcinoid cancer, breast cancer, melanoma, and ovarian cancer." (PMID 33574966, 2021). "Collectively, our results indicated that the potential mechanism of DNA2 action in breast cancer might be regulating the cell cycle, DNA replication, homologous recombination, mismatch repair, nucleotide excision repair, and base excision repair pathways." (PMID 33574966, 2021). "We analyzed 2,509 breast cancers in “cBioportal” and 3,063 breast cancer data in “bc-GenExMiner,” respectively, and got the following conclusion: high expression of DNA2 was closely correlated with ER-, PR-, and HER2+, indicating worse prognosis and therapy effect in breast cancer." (PMID 33574966, 2021). "Additionally, DNA2 partial depletion decreases breast cancer tumorigenicity." (PMID 33662042, 2021). "Furthermore, silencing of DNA2 inhibited cell growth in T47D and MD-MB-231 breast cancer cells and suppressed tumor growth in vivo, indicating DNA2 functioned importantly in breast cancer progression and maybe a potential prognostic marker in breast cancer." (PMID 33574966, 2021). "To test this hypothesis, we inhibited DNA2 with the specific DNA2 inhibitor C5 and/or blocked ATR activation with the ATR inhibitor VE‐821 in several commonly used aggressive cancers cell lines such as MCF7 (breast cancer), and HCT‐116 (colorectal cancer) and H460 (non‐small‐cell lung cancer)." (PMID 29773570, 2018). "Similarly, transformed breast cancer cells (Hs578T and BT549) were more sensitive than MCF10A non-transformed breast epithelial cells to the DNA2 inhibitor." (PMID 28414320, 2017).
melanoma (5 papers, 2017 to 2025). A malignant, usually aggressive tumor composed of atypical, neoplastic melanocytes. "In melanoma brain metastases, heterozygous copy number loss of HR and SSB repair, but no mismatch repair-associated genes, was found, which from the most prevalent genes were APTX, FEN1, GTF2H5, DNA2, MUS81 and TOP3A." (PMID 34885093, 2021). "In addition to melanoma and thyroid cancer, DNA2 is highly expressed in these other tumors." (PMID 40839681, 2025).
ovarian carcinoma (5 papers, 2014 to 2023). A malignant neoplasm originating from the surface ovarian epithelium. "Mutations in DNA2 found in ovarian cancers impair DNA2 activity and depletion of DNA2 in estrogen-responding cells (MCF7) ceases proliferation, unless the cells are supplemented with estrogen." (PMID 25238049, 2014). "Searching the dbGaP database we found four missense mutations in the DNA2 gene in ovarian cancer cases." (PMID 25238049, 2014). "Overexpression of DNA2 is associated with poor outcome in ovarian cancer." (PMID 37756561, 2023). "Indeed, we show that mutations found in ovarian cancers impair DNA2 activity." (PMID 25238049, 2014). "Indeed, we demonstrated that mutations from ovarian cancer cases impair DNA2 activity." (PMID 25238049, 2014). "Neither peritoneal nor other metastatic samples display differential expression of DNA2 compared with primary ovarian carcinoma." (PMID 37756561, 2023). "Most ovarian cancers in Stem-A subtype overexpress DNA2; therefore, high DNA2 expression only has a trend, although not statistically significant, toward shorter survival." (PMID 37756561, 2023). "To validate the synergistic effect of DNA2 inhibitor d16 and PARPi in vivo, we established ovarian cancer MDAH-2774 xenografts in NSG mice and treated the mice with vehicle control, d16 (20 mg/kg, i.p. injection, twice/week), talazoparib (0.5 mg/kg, i.p. injection, daily 5×/week), or both." (PMID 37756561, 2023). "Many studies have reported that DNA replication helicase/nuclease 2 (DNA2) is overexpressed in tumors, such as breast and ovarian cancers." (PMID 34047877, 2021).
pancreatic cancer (4 papers, 2017 to 2024). "DNA2 overexpression has been found in human cancers, including breast and pancreatic cancers, and high levels of DNA2 expression have been associated with poor prognosis." (PMID 31754720, 2020). "Here we demonstrate that DNA2 is overexpressed in pancreatic cancers, one of the deadliest and more aggressive forms of human cancers, where mutations in the KRAS are present in 90–95% of cases." (PMID 28414320, 2017). "Similar to pancreatic cancer patient specimens, the DNA2 protein level was greatly increased in K-RasG12D-activated early pancreatic cancer lesions, suggesting that DNA2 overexpression is an early event during tumorigenesis." (PMID 28414320, 2017). "Previous studies investigating the role of DNA2 in cancer pathogenesis and progression showed that DNA2 overexpression supports breast and pancreatic cancer cell survival by overcoming chemotherapy- or radiotherapy-induced replication stress at the DNA replication fork." (PMID 38331987, 2024). "Targeting DNA2 is proposed as a therapeutic target to control tumor growth in pancreatic cancer." (PMID 34181336, 2021). "In addition, depletion of DNA2 significantly reduces pancreatic cancer cell survival and xenograft tumor growth, suggesting the therapeutic potential of DNA2 inhibition." (PMID 28414320, 2017). "Importantly, the depletion of DNA2 impaired the growth and survival of cells from two pancreatic cancer lines, and also led to increased senescence and apoptosis of these cells." (PMID 28414320, 2017). "Thus, DNA2 overexpression is a common theme in many cancer types including pancreatic cancer and inhibition of DNA2 reduces pancreatic cancer cell survival both in vitro and in vivo." (PMID 28414320, 2017).
Fanconi anemia (3 papers, 2020 to 2023). Fanconi anemia (FA) is a hereditary DNA repair disorder characterized by progressive pancytopenia with bone marrow failure, variable congenital malformations and predisposition to develop hematological or solid tumors. "In our experiments, the most significant upregulated genes included FANCD2, a player in Fanconi anemia (FA), and several genes playing a role in the HR-mediated repair of double-strand breaks (DSBs) such as BARD1, BRCA2, RAD51 and DNA2." (PMID 36672885, 2023).
primordial dwarfism (3 papers, 2019 to 2023). "The first reports of individuals harboring biallelic variants in DNA2 and CRIPT were identified in cohorts of individuals with a clinical diagnosis of primordial dwarfism." (PMID 38021400, 2023). "By extension, impaired RF recovery, incomplete DNA replication, and the resulting cell-proliferation defects in the absence of fully functional DNA2 provide a potential explanation for the involvement of DNA2 mutations in primordial dwarfism." (PMID 33924313, 2021).